CD47 (CD47 molecule)
Diseases named in the same sentence as CD47 in open-access papers (continued):
Sharing a sentence is not in itself a finding about the gene and the disease.
tumor (continued). "In addition, since VT1021 stimulates TSP-1 expression, which binds to CD36/CD47 on the surface of tumor cells, we also investigated the TSP-1 CNV in the NCI database." (PMID 39627379, 2024). "There are distinct mechanisms for targeting macrophages for the utility of anticancer approaches; one approach involves targeting the “don’t eat me signal” (e.g. CD47) on live tumor cells to increase macrophage mediated phagocytosis of tumor cells and thereby promoting destruction of tumor cells." (PMID 39678260, 2024). "Interestingly, when tumour cells were cultured alone, CD47 expression remained unchanged, indicating that MLKL alone does not upregulate CD47 in tumour cells." (PMID 39025845, 2024). "A lower dose of CD47 blockade or IgG4 Fc-based antagonist may ameliorate the adverse effects but will impair the anti-tumor efficacy." (PMID 39335665, 2024). "Since the identification of the CD47-SIRPα axis as the first phagocytosis checkpoint, other phagocytosis checkpoints involved in evasion of tumor cells from phagocytic clearance have been discovered, including the PD-1-PD-L1 axis, the MHC-I-LILRB1 axis and CD24-Siglec-10 axis 3-6." (PMID 38773982, 2024). "While NanoICD effectively induce the exposure of CRT on tumor surface and prompt the endocytosis of tumors by phagocytic cells, its efficacy may still be limited by don’t-eat-me signals, such as CD47." (PMID 38324678, 2024). "The use of SIRPαFc (TTI-621), a decoy receptor that blocks the interaction of CD47 with SIRPα, was shown to provide a therapeutic benefit to patients with SS by significantly reducing the tumor load through the inhibition of the CD47-SIRPα signaling pathway in a clinical trial (NCT02663518)." (PMID 38915099, 2024). "These de novo IgG antibodies could also suppress in vitro tumoroid and in vivo tumor growth in a CD47 knockout context." (PMID 37066426, 2024). "SIRPα functions to recognize overexpressed CD47 on the cell surface of tumor cells." (PMID 38256021, 2024). "This suggests that the clearance of tumor cells and reduced antigen load induced by CD47 × PD‐L1 BisAb may have diverted CD8+ TIL differentiation against an exhausted, dysfunctional state." (PMID 39584189, 2024). "High CD47 expression is associated with poor prognosis, increased epithelial–mesenchymal transition (EMT), tumor invasiveness, and lower response to ICIs in different solid tumor types including oral squamous cell carcinoma, nasopharyngeal carcinoma, TNBC, and NSCLC." (PMID 38785789, 2024). "Nonetheless, tumor growth inhibition by CD47 × PD‐L1 BisAb was primarily mediated by CD8+ T cells." (PMID 39584189, 2024). "Moreover, SG635-SF was more effective in suppressing the growth of SK-OV3 tumor xenografts through leveraging the combined actions of viral oncolysis and CD47 pathway inhibition." (PMID 38970121, 2024). "Our data showed that both stroma cells and tumor cells express CD47." (PMID 38920727, 2024). "Similarly, CD47 protein was widely detected across multiple cell compartments, including tumor cells, CAFs, endothelial cells, and myeloid and T cells." (PMID 38577107, 2024). "Thus, blocking CD47 on the cell surface enhances NK cell-mediated anti-tumor immunity in the hypoxic microenvironment of HCC." (PMID 38297372, 2024). "CD47 is overexpressed to varying degrees in most tumor cells compared to adjacent tissues." (PMID 39652550, 2024). "While the employment of monotherapy, either anti-PD-L1 or anti-CD47, has facilitated the immune response, the incorporation of anti-CD47 with anti-PD-L1 has conspicuously diminished the tumor burden through the augmentation of cytotoxic T cells that secrete intratumoral granzyme B." (PMID 38397971, 2024). "However, anti-CD47 antibodies can competitively inhibit CD47’s binding to SIRPα and mediate macrophage phagocytosis, thereby targeting and killing tumor cells, such as those found in NSCLC." (PMID 38389925, 2024). "The CD47-SIRPα pathway is a crucial immune checkpoint in tumor progression." (PMID 39232806, 2024).
tumor (continued). "We then evaluated the in vivo therapeutic efficacy of SIRPα-Fc in the HSPCs-CDX model, which could better simulate the anti-tumor effect of CD47 blockade in a human immune system." (PMID 39335665, 2024). "We speculate that macrophages polarize to the anti-tumor M1 phenotype upon JHU-083 treatment as a result of CD47 and PD-L1 signaling suppression." (PMID 38386265, 2024). "Dual targeting of CD47 and PD‐L1 has led to promising preclinical results across tumor models." (PMID 39584189, 2024). "CD47 is a checkpoint inhibitor that reduces macrophage function in tumor cells." (PMID 38892305, 2024). "However, angiogenesis is increased in CDX tumor tissues during CD47 blockade, limiting immunotherapy efficacy." (PMID 39335665, 2024). "This led us to speculate that, while tumor-derived factors are critical for regulating the immunosuppressive phenotype of moDCs and M-MDSCs, engagement with CD47 expressed by the TME may be needed to enhance a metabolic shift in these cells." (PMID 38577107, 2024). "Delving into the intricate interplay between CD47 and the tumor immune microenvironment (TIME) to delineate a comprehensive understanding of tumor immune evasion pathways holds promise for the development of tailored therapeutic interventions and the identification of novel immune targets." (PMID 38720108, 2024). "The obtained hMnO2 could generate O2 to relieve tumor hypoxia, thereby suppressing CSCs and reducing the expression of CD47 to enhance immune response." (PMID 38699238, 2024). "Similarly, silencing CD47 and anti-CD47 monoclonal antibody (anti-CD47 mAb) exerted an inhibitory effect on tumor cells." (PMID 38832992, 2024). "Furthermore, the combined treatment of cordycepin and an anti-CD47 antibody significantly curtailed tumor growth and extended the lifespan of tumor-bearing mice." (PMID 39660124, 2024). "In addition to enhanced direct tumor cell killing, anti-CD47 treatments have been shown to repolarize TAMs to an anti-tumor phenotype in preclinical models." (PMID 39596395, 2024). "As a first step assessing phagocytosis, we tested whether phagocytosis of XVir-infected tumor cells by either THP-1-derived macrophages or THP-1-derived immature dendritic cells (imDCs) was increased despite the upregulation of CD47." (PMID 38357194, 2024). "Binding of CD47 to its target receptor, SIRPα, on myeloid cell lineages leads to the initiation of the downstream signaling cascades that inhibit innate immunity anti-tumor responses." (PMID 39742254, 2024). "The ligand of CD47, signal regulatory protein alpha (SIRPα), is mainly expressed on macrophages and when the interaction with CD47 occurs, the downstream signaling within tumor cells results in the dephosphorylation of multiple substrates, keeping tumor cells from phagocytosis by macrophages." (PMID 39003350, 2024). "Tumor cells highly express CD47, a transmembrane glycoprotein, on their surface." (PMID 38672714, 2024). "Importantly, highly diverse mechanisms of malignant transformation and cancer progression can result in different modes of CD47 regulation depending on the tissue type of tumor origin." (PMID 39742254, 2024). "In addition, monoclonal antibodies targeting CD47 on the tumour cells have been demonstrated to activate macrophages and induce phagocytosis of the tumour cells." (PMID 38566987, 2024). "Furthermore, the specificity of CD47-targeted BsAbs limited to certain tumor types underscores the critical importance of precise malignancy identification and classification." (PMID 39040441, 2024). "Interaction of CD47 with the signal regulatory protein-alpha (SIRPα) receptor expressed on many myeloid derived cell lineages activates molecular pathways effectively inhibiting an anti-tumor function of innate immunity." (PMID 39742254, 2024). "Cancer cells are known to highly express ‘‘don't eat me’’ signals such as CD47 that help them escape efferocytosis, and MerTK may facilitate tumor growth in some cancerous conditions." (PMID 38341954, 2024).
tumor (continued). "Furthermore, the IHC results revealed an upregulation of the Foxp1 level in the tumor tissues after anti-CD47 Ab treatment." (PMID 38398223, 2024). "And here, it could be speculated that at the beginning of tumorigenesis, the tumor escapes immunological control through the expression of CD47; that is, it becomes invisible to macrophages, and, subsequently, other mechanisms are involved." (PMID 39201801, 2024). "In contrast, the high-affinity binding mediated by the anti-CEACAM5 arm induces the co-engagement of CD47 resulting in a “guided inhibition” of the CD47-SIRPα interaction between CD47 on CEACAM5-positive tumor cells and SIRPα on e.g., macrophages and natural killer cells." (PMID 38720892, 2024). "However, the anti-tumor activity of SIRPα-CD47 blockers in solid tumors seems limited, suggesting the need for combination therapies to fully exploit the myeloid immune checkpoint in solid tumors." (PMID 38843278, 2024). "Therefore, drugs targeting CD47 or SIRPα can block this signal, restoring the phagocytic function of macrophages, thereby achieving anti-tumor effects." (PMID 38370407, 2024). "Indeed, SIINFEKL+ CD8+ T cells were significantly enhanced by CD47 × PD‐L1 BisAb treatment in the tumor compared to controls but were numerically unchanged in the spleen and MFP." (PMID 39584189, 2024). "In addition, SBsib-711 binds CD47 and PD-L1 on tumor cells, which is applicable in cancer immunotherapy as a checkpoint inhibitor." (PMID 38399416, 2024). "However, their tumour-killing abilities were compromised by the development of phagocytosis resistance in neighbouring tumour cells through the upregulation of CD47 in the highly inflammatory microenvironment (with elevated IL-6 levels)." (PMID 39025845, 2024). "These nanobodies could serve as invaluable tools in cancer research, facilitating a deeper understanding of the CD47–SIRPα signaling axis and its role in tumor progression and immune evasion." (PMID 38247566, 2024). "The addition of anti-CD47 antibodies allows persistent macrophage recruitment to the tumor microenvironment and could be applicable across different tumor types." (PMID 39199554, 2024). "By producing CD47, tumor cells resist phagocytosis by macrophages; as such, inhibiting CD47 could result in increased tumor cell death." (PMID 38279265, 2024). "In this context, an enhanced CD38- and CD47-targeted therapeutic approach that can promote innate immune cell-induced tumor killing potential and overcome anti-CD38 antibody resistance mechanisms may be effective in treating hematologic malignancies." (PMID 38983860, 2024). "Immunosuppressive macrophage signaling is also implicated in the development of antiphagocytic signaling within tumor cells, which is regulated by overexpression of CD47, PD-L1, and beta-2-microglobulin, and allows tumors to avoid macrophage dependent phagocytosis." (PMID 39612029, 2024). "Importantly, we noted that AT3‐OVA cells expressed high levels of CD47 and PD‐L1, along with the expression of these molecules on macrophages and cDC populations isolated from the tumor and spleen." (PMID 39584189, 2024). "Second, CD47-SIRPα signal both inhibits the innate immunity by suppression of macrophage phagocytosis and NK cells’ killing effects, and the adaptive immunity by suppression of tumor antigens cross-presentation and T cell activation." (PMID 38317230, 2024). "The increased level of CD47 on the tumor cell surface is attributed to HIF-1." (PMID 38165484, 2024). "Blocking the CD47-SIRPα pathway with anti-CD47 antibodies enhances phagocytosis of tumor cells." (PMID 38273373, 2024). "As Tug1 sponges miR‐340 and promotes Cd47 in vitro, we further explored whether miR‐340 plays a critical role in regulating tumor growth in vivo." (PMID 38981064, 2024). "CD47 on CD8 + T cells infiltration had an impact on tumor prognosis." (PMID 38720108, 2024).
tumor (continued). "Based on these results, we further assessed whether knockdown Vtn had a synergistic effect with the anti-CD47 antibody treatment on tumor growth inhibition." (PMID 38773982, 2024). "In this study, we envisage that chemotherapy-induced ICD can be combined with other immunotherapy methods, such as inhibition of CD47 expression, a combination of R848, to regulate the immune microenvironment, enhance tumor immunogenicity, and inhibit tumor growth, recurrence, and metastasis." (PMID 39697556, 2024). "In tumor-bearing mice in which CD47 inhibitors are ineffective, injection of Bifidobacterium resulted in a response to anti-D47 treatment In cases where CD47 inhibitors are ineffective in tumor-bearing mice, the administration of Bifidobacterium results in a positive response to anti-D47 treatment." (PMID 38699473, 2024). "CD47 had become a star anti-tumor molecule since its immune checkpoint (IC) identity was revealed." (PMID 38317230, 2024). "The identified M2-like-differentiated macrophages have recently moved into the spotlight of immunotherapy: combined anti-GD2/CD47 therapy to activate Mφ resulted in highly promising anti-tumor activity, accompanied by recruitment of M1-like Mφ and reduced M2-like Mφ." (PMID 38181797, 2024). "To investigate whether combining anti-angiogenic drugs with CD47 blockade could further inhibit tumor growth, we compared the anti-tumor effect of single-agent therapy and combination therapy in the HSPCs-CDX model." (PMID 39335665, 2024). "CD47‐SIRPα axis is an immunotherapeutic target in tumor therapy." (PMID 38477522, 2024). "Pathways that regulate CD47 expression on tumor cells have gained much attention in recent years." (PMID 39194679, 2024). "Furthermore, acetyl‐CoA from FAO upregulates CD47 transcription via the NF‐κB pathway; blocking CPT1 impairs tumor growth and reduces CD47's anti‐phagocytic effect." (PMID 39415848, 2024). "Therefore, engagement of SIRPA on macrophages by CD47 on tumor cells not only suppresses phagocytosis function of macrophages but also elicits the second signal, which would block M2 polarization and preserve M1 TAMs." (PMID 38920727, 2024). "In the treatment-naïve patient cohort, most tumor tissues expressed CD47." (PMID 38493445, 2024). "Many prior discoverieshave indicated the role that macrophagesand the CD47-SIRPα signaling pathway play in OvCa progression.Our hanging drop co-culture spheroids uniquely model the ascites transportof metastatic tumor clusters and situate us to isolate and study therelevant cellular interactions." (PMID 38558434, 2024). "These authors hypothesized that metastatic tumor cells, through expression of the ligand CD47, may recruit M2 macrophages via the SIRPA receptor." (PMID 39516662, 2024). "The CD47/SIRPα axis has been known since 1998 and its role in neoplasms cannot go unnoticed." (PMID 38892394, 2024). "Additionally, we explored the presence of CD47 at low and high tumor grades and assessed the clinical relevance of this molecule in our retrospective cohort." (PMID 38493445, 2024). "Additionally, Bispecific antibodies (BsAbs) simultaneously blocking the CD47-SIRPα axis and binding to the tumor-specific antigen (CD20) have shown promising efficacy with less blood cell destruction in a human NHL-engrafted mouse model." (PMID 39040441, 2024). "Moreover, many CD47-targeted bispecific antibodies that are engineered to specifically target other surface proteins on tumor cells while blocking the CD47-SIRP axis can produce synergistic antitumor effects." (PMID 38464520, 2024). "CD47 engagement induces tumor cell apoptosis through a caspase-independent mechanism." (PMID 38638433, 2024). "Almost all types of tumor cells upregulate CD47 on malignant cells." (PMID 38786045, 2024). "We additionally evaluated whether the check-point molecule CD47, which is considered a negative regulator of phagocytosis, showed any differences in its expression in tumor cells between patients’ subgroups." (PMID 39201801, 2024).
tumor (continued). "One limitation could be an increased expression of CD47 on tumor cell surfaces or an upregulation of alternative phagocytic mechanisms." (PMID 39199554, 2024). "Preclinical models of anti-CD47 therapy may have overestimated efficacy, and the response to treatment can greatly vary among different tumor types." (PMID 38273373, 2024). "CD47 plays a pivotal role in cancer by delivering a "don't eat me" signal to macrophages when binding to its ligand signal-regulatory protein alpha (SIRPα) on tumor cells." (PMID 38475778, 2024). "Likewise, the concomitant administration of Olaparib with anti-CD47 antibody amplified TAM-mediated tumor regression than monotherapy." (PMID 38317230, 2024). "Additionally, it was suggested that CD47 blockade targets both pro-inflammatory (M1-like) and anti-inflammatory (M2-like) macrophage populations in the tumor microenvironment." (PMID 38261139, 2024). "In order to kill cancer cells and sabotage CD47-SIRPa (CD47-signal regulatory protein alpha) connections, the hybrid cell membrane nanovesicles, or hNVs, can interface with circulating tumour cells (CTCs) in vascular lumens and accumulate at the site of resection." (PMID 39720730, 2024). "Similarly, CD276, CD155, CD200, and CD47 inhibit T and NK cell killing and induce an immunosuppressive tumour microenvironment." (PMID 38794316, 2024). "In recent years, the role of CD47 for tumor cells and immune cells has made some progress." (PMID 39652550, 2024). "Therefore, actively exploring effective targets to co-block CD47 is crucial to fully activate macrophages for the phagocytosis of tumor cells." (PMID 38398223, 2024). "Notably, in syngeneic models of CD47/SiRPα blockade, either by injected Abs or coengineered T cells, tumor control (e.g., of MC38) can also be supported by “renewable” infiltration of endogenous T cells." (PMID 38828721, 2024). "Our previous study showed that AZD8055 could act as a small molecule inhibitor of CD47, and that downregulation of CD47 could promote the phagocytosis of tumor cells by macrophages." (PMID 38520730, 2024). "It is known that CD47 helps tumor cells escape from the engulfment of macrophages, while interfering CD47-SIRPα interaction could restore the macrophage-mediated phagocytosis of tumor cells." (PMID 39335665, 2024). "Therefore, revealing mechanisms involved in the regulation of CD47 expression represents a pivotal task in our understanding of tumor progression and immune evasion." (PMID 39742254, 2024). "Camouflaged by CM, PEG2000‐SiNcTI‐Ph/CpG‐ZIF‐8@CM could evade immune surveillance by activating the CD47/SIRPα pathway to target CT26 tumor cells mediated by PD‐1/PD‐L1 interaction." (PMID 38728587, 2024). "Extracellular vesicles, including exosomes, released from CD47-overexpressing normal or tumor cells (transgenic or native), can induce efficient CD47 cross-dressing on pig or human cells, which can interact with SIRPα to inhibit phagocytosis without transmitting harmful cellular signals." (PMID 38426113, 2024). "Several ligands, antibodies, or short peptide-modified nanocarriers, including transferrin, folic acid, and anti-CD47 antibodies, with high specificity and affinities have been developed, considering the specific high expression of receptors or protein antigens on tumor cell membranes." (PMID 38389925, 2024). "Moreover, the tumor volume was slightly increased in the combination therapy group compared to the anti-CD47 Ab group." (PMID 38398223, 2024). "Here we tested whether combination of SIRPα-CD47 blocker with antibody-drug conjugate bearing a topoisomerase I inhibitor DXd (DXd-ADC) would enhance anti-tumor activity in solid tumors." (PMID 38843278, 2024). "Furthermore, targeting CD47 was validated to promote the normalization of tumor vasculature by increasing the infiltration of CD4+ T cells." (PMID 38398223, 2024). "Conversely, SIRPα-containing EVs can enhance phagocytosis by blocking CD47 in tumor cells." (PMID 38543204, 2024).